RHEB (Ras homolog, mTORC1 binding)
Diseases named in the same sentence as RHEB in open-access papers (continued):
Sharing a sentence is not in itself a finding about the gene and the disease.
Fibroadenoma (1 paper, 2021). A benign tumor of the breast characterized by the presence of stromal and epithelial elements. "Evidence also suggest an elevated expression of RHEB in epithelial cells of fibroadenomas providing an association of RHEB with insulin/AKT/TOR signaling pathway in benign tumor development." (PMID 33593445, 2021).
Focal cortical dysplasia (1 paper, 2023). A type of malformation of cortical development that primarily affects areas of neocortex. "One patient diagnosed with Type II focal cortical dysplasia (FCD) had a somatic variant in RHEB, a gene that is known to play a major role in the mTOR signaling pathway and has been altered in patients with FCD13." (PMID 36631516, 2023).
head and neck cancer (1 paper, 2025). A primary or metastatic malignant neoplasm affecting the head and neck. "Among them, 6 genes were highly expressed in head and neck cancers, namely SLC1A5, ETS1, NDRG1, RHEB, HIF1A and CDH2." (PMID 41317550, 2025).
Hepatitis (1 paper, 2019). Inflammation of the liver. "Overall, circRNA-100338 is closely associated with poor prognosis of hepatitis B-related HCC by activating mTOR signaling pathway via circRNA-100338/miR-141-3p/RHEB axis." (PMID 31157168, 2019).
liver fibrosis (1 paper, 2020). "To examine the role of other targets in the therapeutic effect of miR-451/miR-185 agomirs, we detected the protein expression of three representative liver fibrogenesis-related target genes including c-myc, RHEB and RICTOR in CCl4-induced liver fibrosis mice." (PMID 32467578, 2020).
lung carcinoma (1 paper, 2025). "Among them, the RHEB gene is involved in six pathway processes and is strongly related to lung cancer." (PMID 40149413, 2025).
malignant mesothelioma (1 paper, 2022). A malignant neoplasm of the pleura or peritoneum, arising from mesothelial cells. "Several studies also found that high expression of exogenous RHEBL1 promoted the growth of malignant mesothelioma cells and probed that RHEB-mTORC1 signaling has a pro-carcinogenic effect." (PMID 36386821, 2022).
malnutrition (1 paper, 2023). Inadequate nutrition resulting from poor diet, malabsorption, or abnormal nutrient distribution. "As an evolutionarily conserved, lysosomal-driven catabolic response to malnutrition, autophagy is inhibited by trophic factors (the TSC-Ras homolog enriched in brain/RHEB pathway) or amino acid supply (the phosphoinositide 3-kinase/PI3K-RHEB pathway) that activate mTOR." (PMID 36675042, 2023).
mesothelioma (1 paper, 2018). A usually malignant and aggressive neoplasm of the mesothelium which is often associated with exposure to asbestos. "On the other hand, no activating mutations in the MTOR, nor the RHEB genes, have been identified in mesothelioma cells to date, although such mutations were shown to cause the hyper-activation of mTORC1 observed in mesothelioma." (PMID 29587439, 2018).
multiple myeloma (1 paper, 2024). "Consolidating KMS-11 as our primary experimental model for investigating the role of p52 in multiple myeloma, we identified several p52-regulated essential genes upregulated in patients, i.e. RGS1 and RHEB, whose expression have been linked to poorer prognosis in MM patients and other cancers." (PMID 38514625, 2024).
Parkinsonism (1 paper, 2024). Characteristic neurologic anomaly resulting from degeneration of dopamine-generating cells in the substantia nigra, a region of the midbrain, characterized clinically by shaking, rigidity, slowness of movement and difficulty with walking and gait. "Moreover, in the mTOR-MAPK signaling model for parkinsonism-T2DM, we observed higher glycolysis activity and an increase in the inactivated form of RHEB, and the activation of anaerobic glycolysis." (PMID 39429779, 2024).
Peutz-Jeghers syndrome (1 paper, 2018). An autosomal dominant disorder caused by pathogenic variants in the STK11 gene, characterized by hamartomatous polyps in the gastrointestinal tract, mucocutaneous pigmentation and increased risk of GI and extra-GI malignancies. "Aberrant RHEB/mTORC1 signaling has been linked to many overgrowth diseases including Lymphangioleiomymoatosis (LAM), Tuberous Sclerosis (TS), Peutz-Jeghers syndrome (PJS) and benign tumor formation." (PMID 29320991, 2018).
renal angiomyolipoma (1 paper, 2011). "We conclude that sporadic renal angiomyolipoma usually have mutations in TSC2, but not TSC1 or RHEB, and have no other common genomic events, among those we searched for." (PMID 21949787, 2011).
rhabdomyosarcoma (1 paper, 2024). A rare aggressive malignant mesenchymal neoplasm arising from skeletal muscle. "This included a solid pseudopapillary neoplasm of pancreas (everolimus for high Ras homolog enriched in brain (RHEB)), EPN (bevacizumab for high VEGFA) and rhabdomyosarcoma (temsirolimus/vinorelbine/cyclophosphamide for high AKT2)." (PMID 38844796, 2024).
squamous carcinoma (1 paper, 2019). "ATF6 modulates cancer cell dormancy via the activation of Ras homolog enriched in brain (RHEB) and mTOR, in which ATF6 not only plays a role as a key survival factor for quiescent squamous carcinoma cells, but is also pivotal for the adaptation of dormant cells to chemotherapy." (PMID 31739582, 2019).
Uterine Corpus Endometrioid Carcinomas (1 paper, 2016). "These mutations are mostly represented by Y35N hosted by RHEB and found present in Kidney Renal Clear Cell and Uterine Corpus Endometrioid Carcinomas in TCGA patients." (PMID 26860319, 2016).
tumor (27 papers, 2009 to 2025). "Elevated levels of RHEB or abnormal activation of the mTORC1 signal pathway have been linked to increased tumor proliferation." (PMID 39600313, 2024). "Additionally, wildtype RHEB, wildtype mTOR, and another tumour-associated mutant, mTORR2505P induced pT401, albeit to a lesser extent." (PMID 39223665, 2024). "It is well-established that RHEB is a small GTPase that directly activates mTORC1 activity, but is negatively regulated by tumor suppressors TSC1/TSC2." (PMID 39762645, 2025). "RHEB has been found to impact the tumor microenvironment by modulating the mTORC1 signaling pathway." (PMID 39600313, 2024). "Since FTase contributes to oncogenesis by interacting with RAS and RHEB genes, FTase inhibitors have been investigated as an anti-tumor treatment." (PMID 38756650, 2024). "RHEB, overexpressed in tumor tissues, is a GTP-binding protein positively regulating mTOR activation." (PMID 37444412, 2023). "BFAL1 serves as a ceRNA to sponge miR-155-5p and miR-200a-3p and regulates the expression of RHEB, activates the RHEB/mTOR signaling pathway, and promotes tumor growth." (PMID 37280524, 2023). "RHEB-overexpressing cells also demonstrated enhanced in vitro cytotoxicity and degranulation toward tumor cells over the pHe range of 6.6 to 7.4." (PMID 36380966, 2022). "Previous studies have confirmed that the five autophagy-related genes (BIRC5, SQSTM1, HDAC1, RHEB, and ATIC) are associated with tumor proliferation, apoptosis, and resistance to anticancer agents in HCC patients." (PMID 35573678, 2022). "RHEB binds and activates the mechanistic target of rapamycin (mTOR), a regulator of tumor cell growth, survival, and metabolism." (PMID 34771475, 2021). "Taken together, ETBF orchestrates the BFAL1, miR-155-5p/miR-200a-3p, and the RHEB/mTOR pathways to regulate CRC tumor growth." (PMID 31515468, 2019). "In another study, circ_100338 is reported to be up-regulated in HCC tissues, which is related to the poor prognosis of HCC patients; mechanistically, circ_100338 plays a tumor-promoting role via regulating the miR-141-3p/RHEB axis and controlling mTOR signal pathway." (PMID 34002672, 2021). "Like circRNA-100338, RHEB was also up-regulated in tumor tissues." (PMID 31157168, 2019). "AKT1 then inhibits the tumour-suppressor TSC1/2 complex, releasing its inhibition on RHEB, thereby activating mTORC1." (PMID 39568072, 2024). "Mechanistically, ETBF promoted tumor growth via BFAL1 by activating the Ras homolog, which is the MTORC1 binding/mammalian target of the rapamycin (RHEB/mTOR) pathway." (PMID 31515468, 2019). "BFAL1 mediates ETBF-induced tumor growth by activating the Ras homolog, which is the MTORC1 binding/mammalian target of the rapamycin (RHEB/mTOR) pathway." (PMID 31515468, 2019). "This in turn activates RheB and mTOR/S6K1 to mediate cellular transformation and tumor formation." (PMID 27409169, 2016). "Furthermore, inhibition of other farnesylated proteins, such as RHEB and RHOB, may help overcome resistance to standard therapies in SCCs and additional tumor types." (PMID 34771475, 2021). "However, while the lentivirus-mediated RNAi knockdown of RHEB decreased cell proliferation, migration and colony forming ability in vitro, no impact on tumor growth in vivo was observable." (PMID 29050215, 2017). "However, interestingly, inactivation of RHEB failed to impact tumor growth in vivo." (PMID 29050215, 2017).
cancer (25 papers, 2014 to 2025). A tumor composed of atypical neoplastic, often pleomorphic cells that invade other tissues. "Previous analysis of cancer cytogenetic and transcriptomic databases indicated that RHEB mRNA expression was up-regulated in different carcinoma histotypes and was associated with poor outcomes in multiple types of malignancies." (PMID 32807131, 2020). "Recent work on cancer genome databases has revealed a reoccurring mutation in RHEB at the Tyr35 position, and a recent study points to the oncogenic potential of this mutant that involves activation of RAF/MEK/ERK signaling." (PMID 29320991, 2018). "This relationship is greatly affected by the Y35N point mutation, which results in cellular cancer transformation due to decreased RHEB Y35N-BRAF interaction and increased BRAF-CRAF dimerization." (PMID 29320991, 2018). "For the presence of the Y35N mutation, RHEB was recently highlighted as a novel cancer gene involved in cell proliferation, and cancer associated mutations in RHEB inducing mTORC1 activity have been reported." (PMID 26860319, 2016). "Second, we predict that cancers with activating mutations in RHEB, or inactivating mutations in DEPDC5, NPRL2, and NPRL3, will show similar strong response to rapalogs." (PMID 26137524, 2015). "Mutations in RHEB are uncommon in many cancers, despite its central role in regulating downstream mTOR activation." (PMID 26255626, 2015). "Similar to the engineered Y35A and Y35F mutations, we found that the cancer-associated Y35N RHEB mutation increased the rate of intrinsic GTP hydrolysis by ~2.5 fold, due to release of the autoinhibitory function of Y35." (PMID 26255626, 2015). "These mutations are thought to lead to activation of RHEB, which in turn promotes activation of the mTOR gene, one downstream effect of which is vastly increased protein production and much larger cancer cells." (PMID 25041817, 2014). "The recurrent mutation of RHEB Y35 in cancers underscores the importance of this residue, and illustrates that the unique biochemical properties of RHEB lead to a different mutational hotspot relative to RAS, in which the majority of mutations affect G12, G13 and Q61." (PMID 26255626, 2015). "Particularly, the key regulators of mTOR signaling such as LAMTOR2, LAMTOR5, YWHAB, LAMTOR1, FKBP1A, and RHEB were also upregulated in the cancer cells of intra‐tumoral TLS‐low group." (PMID 38498682, 2024). "RHEB functions as a major upstream activator of the mTOR pathway, which promotes metabolic reprogramming of glucose and glutamine in cancer cells, ensuring rapid growth and proliferation of neoplastic cells." (PMID 35701309, 2022). "The crucial role of RHEB in regulating growth and survival through mTORC1 makes it a targetable site for anti-cancer therapeutics." (PMID 34445471, 2021). "Our results showed that RHEB, a key regulator of mTOR signaling, exhibited a high expression level in cancer samples, compared with normal and adjacent normal samples." (PMID 32807131, 2020). "Various cancer types have been shown to carry druggable targets for mTOR inhibitors, including mutations in MTOR, TSC1, TSC2, NF1, PI3KCA, PIK3CG, STK11, and RHEB." (PMID 31443247, 2019). "RHEB is a key intermediate in the PTEN pathway on which it has an inhibitory effect, and is overexpressed in many cancers where it has been variously associated with increased cell proliferation, hyperplasia and fibrosis." (PMID 31889146, 2019). "RHEB Y35N expressing cells undergo cancer transformation due to decreased interaction between RHEB and BRAF resulting in overactive RAF/MEK/ERK signaling." (PMID 29320991, 2018). "More than 40 % of the DEGs (32 out of 79 genes) have been proven to have prognostic values with at least one type of cancer, including well-known oncogenes RHEB and MYCN." (PMID 27769251, 2016). "Our analysis of cancer genome databases, also led us to identify a recurrent point mutation in RHEB (Y35N), reported in RCC and in several other cancers." (PMID 26255626, 2015).
cancer (continued). "Using publicly available databases of cancer genome sequence data, we examined a cluster of mutations in MTOR specific to RCC located in the FAT domain of mTOR and a point mutation in the RHEB gene." (PMID 26255626, 2015). "Finally, RHEB knockdown reversed the promoting effects of CREB3L4 on the proliferation of cancer cells." (PMID 38303702, 2024). "Therefore, in this study we aimed to reveal the kinetics of RHEB to mTOR, which can inform the development of new anti-cancer drugs." (PMID 34445471, 2021). "Further, to investigate this association, we evaluated the correlation between SESN2 and mTOR pathway-related markers, including RPTOR, MTOR, and RHEB, by analyzing RNA expression data from cancer patients using the Gene Expression Profiling Interactive Analysis (GEPIA) database." (PMID 32899752, 2020). "ATF6 induces the expression of RHEB, which activates mTOR signaling and renders therapeutic resistance to dormant cancer cells, suggesting targeting ATF6 might be one of the valuable therapeutic strategies." (PMID 31739582, 2019). "We next looked at the ability of RHEB Y35N to transform normal cells into cancer cells." (PMID 29320991, 2018). "An oncogenic mutant of RHEB was identified from the analysis of human cancer genome databases." (PMID 29320991, 2018). "FTase proteins (FNTA and FNTB) as well as eight of the 116 PFPs are known cancer-relevant proteins as per COSMIC Cancer Gene Census49 or TCGA50 (KRAS, HRAS, NRAS, RHEB, RHOA, DDX3X, ARID2, and SAV1)." (PMID 39995872, 2025). "This is followed by CFTR (18 cancer types) and four other genes that were amplified in 17 cancer types (ADIPOR2, LEP, PRKAG2 and RHEB)." (PMID 32807122, 2020). "This pattern of heterogeneity was similar when considering a broader list of pan-cancer driver genes, with private amplification events seen in ERBB3, RHEB, SOS1, SOS2, and EZH2." (PMID 30348992, 2019). "We also examined the binding of the mutant RHEB Y35N to AMPK, as a previous report suggested that RHEB Y35N transforms cancer cells through an interaction with AMPK." (PMID 29320991, 2018). "The four ARGs RHEB, NPC1, PRK3D, and CLN3 have not been reported in previous studies on HCC or other cancers." (PMID 37370041, 2023).
infection (1 paper, 2025). The state of being infected such as from the introduction of a foreign agent such as serum, vaccine, antigenic substance or organism. "EVA71 infection recruits mTOR to lysosomes to promote ras homolog enriched in brain (RHEB) interaction and activation via the phosphoinositide 3-kinase (PI3K)/protein kinase B (AKT)/Tuberous sclerosis complex 2 axis." (PMID 40869312, 2025).
kidney diseases (1 paper, 2025). "Insight from this study could potentially mean that some of the drugs that are used for treatment of kidney diseases involving VEGFA and RHEB may potentially increase the risk of developing T2D among Africans." (PMID 40524645, 2025).
neurodegenerative disease (1 paper, 2018). A disorder of the central nervous system characterized by gradual and progressive loss of neural tissue and neurologic function. "RHEB is involved in neurodegenerative diseases, such as Huntington’s disease (HD)." (PMID 30558189, 2018).
prostate (1 paper, 2016). "RHEB acts as a proto-oncogene in the appropriate genetic milieu and signaling context, and its overexpression cooperates with PTEN haploinsufficiency to promote prostate tumorigenesis." (PMID 27769251, 2016).
psychiatric disorder (1 paper, 2021). A disorder characterized by behavioral and/or psychological abnormalities, often accompanied by physical symptoms. "Furthermore, we applied this assay to the investigation of psychiatric disorder-associated mutations of RHEB (RHEB/P37L and RHEB/S68P), revealing that both mutations cause an increase in the ratio of the GTP-bound form in cells." (PMID 34801548, 2021).
RHEB also shares sentences with these, for which no sentence is quoted: Insulin resistance (3 papers); glioma (2); renal cell carcinoma (2); benign tumor (1); bipolar disorder (1); breast adenocarcinoma (1); cardiomyopathy (1); childhood ovarian dysgerminoma (1); chordoma (1); cortical dysplasia (1); cyst (1); developmental and epileptic encephalopathies (1); dyspepsia (1); focal epilepsies (1); gastric adenocarcinoma (1); glioblastoma (1); hemimegalencephaly (1); Hypercholesterolemia (1); hypertrophy (1); infarction (1); intellectual disability syndrome (1); ischemic stroke (1); kidney cancer (1); knee osteoarthritis (1); leukoplakia (1); lung adenocarcinoma (1); Macrocephaly (1); macular degeneration (1); melanoma (1); nasopharyngeal carcinoma (1).
A further 10 diseases each share a sentence with RHEB in 1 paper.